DNMT3B (DNA methyltransferase 3 beta)
Description:
Required for genome-wide de novo methylation and is essential for the establishment of DNA methylation patterns during development. DNA methylation is coordinated with methylation of histones. May preferentially methylates nucleosomal DNA within the nucleosome core region. May function as transcriptional co-repressor by associating with CBX4 and independently of DNA methylation. Seems to be involved in gene silencing (By similarity). In association with DNMT1 and via the recruitment of CTCFL/BORIS, involved in activation of BAG1 gene expression by modulating dimethylation of promoter histone H3 at H3K4 and H3K9. Isoforms 4 and 5 are probably not functional due to the deletion of two conserved methyltransferase motifs. Functions as a transcriptional corepressor by associating with ZHX1. Required for DUX4 silencing in somatic cells.
Synonyms: M.HsaIIIB; FSHD4; ICF; ICF1
Tractability: Small molecule: a structure with a bound ligand is known; a high-quality ligand is known; it belongs to a druggable protein family. PROTAC: UniProt records ubiquitination sites on it; ubiquitination databases record sites on it; a small molecule that binds it is known.
Target class: Reader; Methyl-lysine/arginine binding protein; Epigenetic regulator; PWWP domain
Gene: Protein-coding gene on chromosome 20 (32,762,385 to 32,809,359, forward strand). Ensembl gene ENSG00000088305.
Subcellular location: Nucleus
Subcellular location (Human Protein Atlas): Nucleoplasm
Pathways (Reactome):
Gene expression (Transcription): DNA methylation; NoRC negatively regulates rRNA expression; PRC2 methylates histones and DNA
Disease: Defective pyroptosis
Metabolism of proteins: SUMOylation of DNA methylation proteins
Gene Ontology:
Molecular function: DNA (cytosine-5-)-methyltransferase activity; protein binding; transcription corepressor activity; DNA (cytosine-5-)-methyltransferase activity, acting on CpG substrates; DNA binding; DNA-methyltransferase activity; methyltransferase activity
Biological process: negative regulation of transcription by RNA polymerase II; positive regulation of gene expression; regulation of gene expression
Cellular component: catalytic complex; nucleoplasm; nucleus
Genetic constraint (gnomAD): Loss-of-function variants: 37 observed, 122.84 expected, observed/expected ratio (o/e) 0.3, 90% interval 0.23 to 0.4. The upper end of that interval is the gene's LOEUF score, 0.4, which puts it in group 1 of 6, group 1 being the genes least tolerant of losing a copy. Missense variants: 878 observed, 1,193.5 expected, observed/expected ratio (o/e) 0.74, 90% interval 0.69 to 0.78. Synonymous variants: 412 observed, 466.93 expected, observed/expected ratio (o/e) 0.88, 90% interval 0.81 to 0.96.
Gene-disease validity (ClinGen):
ClinGen rates the evidence that DNMT3B causes each of these diseases.
immunodeficiency-centromeric instability-facial anomalies syndrome 1 (autosomal recessive): Definitive.
Homologues: Orthologues: chimpanzee DNMT3B (100% identical), macaque DNMT3B (97% identical), dog DNMT3B (93% identical), pig DNMT3B (93% identical), rabbit DNMT3B (92% identical), mouse Dnmt3b (84% identical), rat Dnmt3b (83% identical), mouse Dnmt3c (68% identical), rat Dnmt3c (66% identical), zebrafish dnmt3bb.1 (54% identical), guinea pig DNMT3B (53% identical). Paralogues in human: DNMT3A (50% identical), DNMT3L (17% identical), PWWP2A (12% identical), PWWP2B (9% identical).
Diseases named in the same sentence as DNMT3B in open-access papers:
DNMT3B is named in the same sentence as 308 diseases in open-access papers, as found by Europe PMC text mining. Sharing a sentence is not in itself a finding about the gene and the disease. The quoted sentences say what the papers report.
breast carcinoma (132 papers, 2004 to 2026). "METHODS: This nested case‒control study, conducted within the Arkansas Rural Community Health study (ARCH) cohort, examined the associations between polymorphisms in DNMT1, DNMT3A, and DNMT3B and breast cancer risk." (PMID 41663987, 2026). "DNA methyltransferases, such as DNMT1, DNMT3A, and DNMT3B, have been implicated in the progression of multiple malignancies including breast cancer and acute myeloid leukemia." (PMID 40427627, 2025). "The present study confirms that expression of the DNMT3B gene alone, independently of the other marker genes, is also associated with a poor prognosis in breast cancer patients." (PMID 40585280, 2025). "Amplification of the DNMT3B gene is observed in breast cancer cells and has been implicated in resistance to DNA-demethylating therapeutics, e.g., 5-azacytidine (brand name Vidaza®), decitabine, and SGI-1027." (PMID 39334883, 2024). "Gene amplification and protein overexpression of DNMT3B are associated with decreased sensitivity to decitabine and azacytidine in pancreatic and breast cancer cell lines." (PMID 38368287, 2024). "Concerning the hypermethylation, we observed that the induction of MG stress caused an elevated DNMT3B protein level resulting, at least in part, from a prolonged cellular half-life in glycolytic and metastatic breast cancer cells." (PMID 36998085, 2023). "GLO1-depleted breast cancer cells showed elevated expression of DNMT3B methyltransferase and significant loss of metastasis-related tumor suppressor genes, as assessed using integrated analysis of methylome and transcriptome data." (PMID 36998085, 2023). "Up-regulation of the expression and activity of DNMTs, and particularly DNMT3B, has been associated with the acquisition of a hypermethylator signature in breast cancer." (PMID 36998085, 2023). "DNMT3B gene amplification was observed in breast cancer cells and was associated with resistance to DNA demethylating drugs, including Decitabine, 5-azacytidine (Vidaza), and SGI-1027." (PMID 35620052, 2022). "Emerging evidence has showed that the expression of DNMT3A and DNMT3B is linked to clinical features in breast cancer patients." (PMID 35620052, 2022). "It is necessary to mention that DNMT3A and DNMT3B have mutation and amplification in breast cancer patients." (PMID 35620052, 2022). "The earlier reports have shown that the aberrant DNA methylation activity of DNMT3B is linked to the development and progression of breast cancer." (PMID 35360070, 2022). "Several studies have also indicated BRCA1 epigenetic inactivation caused poor survival was related with increased DNMT3B in sporadic breast cancers." (PMID 35620052, 2022). "LncRNA H19 depletion promoted the interaction between DNMT3B and Beclin 1 promoter, causing the Beclin 1 DNA methylation, decreasing tamoxifen resistance due to autophagy inhibition in breast cancer." (PMID 35620052, 2022). "Here, we demonstrated that miR-29c targeted the 3′UTR of DNMT3B and inhibited its expression, and that both miR-29c expression and DNMT3B expression were associated with the survival rate of patients with breast cancer." (PMID 29796115, 2018). "Study showed that there was significantly reduced expression of miR-29c in basal-like breast cancers compared to other breast cancer molecular subtypes and that miR-29c was associated with DNMT3B and methylation of genes." (PMID 29796115, 2018). "It is unclear if there is an association between miR-29c and DNMT3B, and what regulatory mechanisms of miR-29c and DNMT3B occur in breast cancer cells." (PMID 29796115, 2018). "Overexpression of DNMT3B in tumors is a frequent observation (DNMT3B is overexpressed in 30% of breast cancers), associated with the down-regulation of its targets." (PMID 30406101, 2018).
breast carcinoma (continued). "Our results add to the complexity of this relationship, as methylation of the promoter of miR-29c in basal-like breast cancer can decrease miR-29c expression, and, therefore, cause deregulation and over-expression of DNMT3b." (PMID 26539832, 2015). "Many basal-like breast cancers exhibit the silencing of genes associated with DNMT3b protein over-expression." (PMID 24297604, 2014). "Our results have shown that in comparison to the homozygous CC genotype carriers the DNMT3B-CT genotype has a significantly lower risk for breast cancer (OR=0.515, 95% CI=0.267-0.994, P=0.048)." (PMID 24850984, 2014). "In this study we have investigated the correlation between the 46359C→T polymorphism in the DNMT3B gene and the risk of breast cancer incidence among sporadic breast cancer patients in Fars Province, Southern Iran." (PMID 24850984, 2014). "Together, these findings strongly suggest that the molecular mechanism governing the DNMT3b-mediated aberrant DNA hypermethylation in primary breast cancer involves the loss of post-transcriptional regulation of DNMT3b by regulatory miRs." (PMID 24297604, 2014). "Basal-like breast cancers frequently express aberrant DNA hypermethylation associated with concurrent silencing of specific genes secondary to DNMT3b overexpression and DNMT hyperactivity." (PMID 24297604, 2014). "In the case–control study presented herein, we correlated genetic polymorphisms in three genes, DNMT1, DNMT3A and DNMT3B, with clinical parameters to consider the risk of female Caucasians developing breast cancer." (PMID 23638630, 2013). "This is in accordance with other studies, which revealed an association of over-expressed DNMT3B levels and the development of breast cancer and other malignancies." (PMID 23638630, 2013). "A hypermethylation defect associated with DNMT hyperactivity and DNMT3b overexpression characterizes a subset of breast cancers and breast cancer cell lines." (PMID 22664488, 2012). "In conclusion, the molecular mechanism governing the DNMT3b-mediated hypermethylation defect in breast cancer cell lines involves the loss of post-transcriptional regulation of DNMT3b by regulatory miRs." (PMID 22664488, 2012). "The purpose of this study was to elucidate the molecular mechanism governing the overexpression of DNMT3b associated with the expression of hypermethylation defect in breast cancer." (PMID 22664488, 2012). "In conlcusion, the molecular mechanism governing the DNMT3b-mediated hypermethylation defect in breast cancer cell lines involves the loss of post-transcriptional regulation of DNMT3b by regulatory miRs." (PMID 22664488, 2012). "The results of the present study strongly suggest that loss of regulatory miR expression contributes to DNMT3b overexpression in hypermethylator breast cancer cell lines." (PMID 22664488, 2012). "We previously showed that, among the three DNA methyltransferases (DNMT1, DNMT3A and DNMT3B), only DNMT3B overexpression is associated with poor outcome in breast cancer." (PMID 15606925, 2004). "Polymorphism C46359T in the DNMT3B promoter has been registered in patients with breast cancer." (PMID 39334883, 2024). "Additionally, it has been found that intronic variant rs2424908 in DNMT3B correlates with an elevated risk of breast cancer." (PMID 39334883, 2024). "To summarize, TEQUILA-seq identified a subtype-associated transcript isoform of DNMT3B, which may have a global effect on DNA methylation of the basal B subtype of breast cancer." (PMID 37553321, 2023). "In addition, mutations in DNMT3A and DNMT3B and knock outs are also frequently associated with hypomethylation, while overexpression of DNMT3B is associated with hypermethylation in gastric and breast cancer cell lines." (PMID 37234978, 2023).
breast carcinoma (continued). "Although the expressional regulation of its target genes such as DNMT1, DNMT3A and DNMT3B has been reported in breast cancer cells, one of its notable underlying mechanisms for the progression of malignancy is its binding with its target proteins and regulation of their activity." (PMID 38060527, 2023). "Similarly, miR-124a-3 hypermethylation was associated with high expression of DNMT3B and linked to aggressive and advanced stages in breast cancer patients." (PMID 35620052, 2022). "We also discuss the SNP and mutations of DNMT3A and DNMT3B in breast cancer." (PMID 35620052, 2022). "Moreover, the heterozygous genotypes of rs2424908 in DNMT3B was linked to decreased risk of breast cancer in Han Chinese women." (PMID 35620052, 2022). "In a British population, the C46359T polymorphism in the DNMT3B promoter in breast cancer cases was reported by investigation of 352 breast cancer patients and 258 controls, indicating that individuals with T allele in DNMT3B have a high risk of breast cancer development." (PMID 35620052, 2022). "miR-29c regulated DNMT3B which was associated with methylation of genes in breast cancers." (PMID 29796115, 2018). "Therefore, we investigated the association between DNMT3B genotype and the risk of breast cancer incidence among sporadic breast cancer patients in Fars Province, Southern Iran." (PMID 24850984, 2014). "We analyzed breast cancer cell lines for differential expression of regulatory miRs to determine if loss of miR-mediated post-transcriptional regulation of DNMT3b represents the molecular mechanism that governs the overexpression of DNMT3b that drives the hypermethylation defect in breast cancer." (PMID 22664488, 2012). "Recently, several studies showed that some of SNPs in the DNMT3B gene may influence DNMT3B activity on DNA methylation, thereby modulating the susceptibility to lung cancer, breast cancer and gastric cardiac adenocarcinoma." (PMID 18662374, 2008). "Moreover, high expression of DNMT3B at mRNA level might be associated with lymph node diagnosis for breast cancer patients." (PMID 35620052, 2022). "Using differential high resolution melting analysis, one study revealed that DNMT3B promoter methylation was linked to cancer type, tumor size, histologic grade, suggesting that DNMT3B promoting methylation could predict diagnostic and prognostic biomarker for breast cancer." (PMID 35620052, 2022). "The altered expression of DNMTs, encoding DNMTs (DNMT1, DNMT3a, and DNMT3B) could result in global changes of methylation in leukemia cells and breast cancer stem-like cells, while DNMT1, DNMT3A, and DNMT3B are all upregulated in most cancer types (8, 6, and 9, respectively) in this study." (PMID 31828117, 2019). "DNMT3B SNP (C501T, rs406193) showed a significant difference among cases and controls (P value = 0.05) with the T allele (variant) associated with a reduced risk of developing breast cancer, while the statistical analysis of the correlation with clinical parameters was not significant." (PMID 23638630, 2013). "The current results strongly support the suggestion that loss of miR expression may account for the DNMT3b-mediated hypermethylation defect among breast cancer cell lines that is characterized by methylation-dependent loss expression of methylation-sensitive biomarker genes." (PMID 22664488, 2012). "Given the linkage between basal-like breast cancers and expression of the hypermethylation defect, loss of regulatory miR expression leading to DNMT3b overexpression may represent a very early and significant molecular alteration during the natural history of breast carcinogenesis." (PMID 22664488, 2012). "We have shown that the downregulation of GATA3 in breast cancer can be controlled by an aberrant activation of DNMT3B, which induces aberrant methylation in the promoter region of GATA3, in the absence of deleterious somatic alterations." (PMID 40585280, 2025).
breast carcinoma (continued). "According to our results, the gene GATA3 appears to be the main target for silencing in the DNMT3B+ aggressive forms of breast cancer, with twice the frequency of deleterious somatic alterations compared to the other genes in our selection." (PMID 40585280, 2025). "Increased expression of DNMT1, DNMT3A, and DNMT3B was found in various cancers such as breast cancer, pancreatic cancer, lung cancer, hematological malignancies, and head and neck squamous cell carcinoma." (PMID 40507223, 2025). "Our results presented above suggest that the aberrant activation of DNMT3B in breast cancer induces a hypermethylation of CpG rich DNA regions in the promoters of several onco-suppressor genes, responsible for the more aggressive profiles of tumour cells." (PMID 40585280, 2025). "We investigated the role of ectopic activation of the DNA methyltransferase 3β (DNMT3B) in breast cancer." (PMID 40585280, 2025). "Our previous work identified the embryonic stem cell-specific gene DNMT3B, a de novo DNA methyltransferase, as aberrantly activated in breast cancer, correlating with aggressive tumour behaviour and high relapse risk, regardless of molecular subtype." (PMID 40585280, 2025). "DNA methylation is facilitated by DNA methyltransferases (DNMTs) such as DNMT1, DNMT3A, and DNMT3B, all of which are overexpressed in breast cancer patients with advanced clinical disease stages." (PMID 40427627, 2025). "For example, in prostate cancer cells DNMT1 was shown to play a tumor-suppressive role while DNMT3B displayed oncogenic function by inducing EMT-associated phenotypes in head and neck squamous cell carcinoma, breast cancer, and ovarian cancer cells." (PMID 40764968, 2025). "In conclusion, we discovered that aberrant activation of DNMT3B in breast cancer regulates the methylation of the promoter region of GATA3 and can repress this gene." (PMID 40585280, 2025). "We found that, compared with normal tissues, the protein levels of DNMT3A and DNMT3B in breast cancer tissues were increased, and the protein level of TAT was decreased." (PMID 39334853, 2024). "Recently, it was also shown that DNMT3B is induced in metastatic cells and facilitates distant colonization and that high DNMT3B levels are correlated with poor patient survival and more aggressive subtypes of breast cancer." (PMID 37592220, 2023). "Based on these observations, miR-29c exerted its functional role in breast cancers by modulating the DNMT3B/TIMP3/STAT1/FOXO1 pathway." (PMID 37705098, 2023). "We found that this DNMT3B signature effectively segregated breast cancer cells under MG stress from control cells." (PMID 36998085, 2023). "Studies have shown that DNMT1, DNMT3A and DNMT3B are usually highly expressed in patients with advanced breast cancer." (PMID 37298314, 2023). "In conclusion, miR-221 plays a role in promoting tumorigenicity in breast cancer by modulating stemness characteristics, primarily by exerting control over the expression of DNMT3b." (PMID 37705098, 2023). "Conclusively, DNMT3B suppression through knockdown techniques resulted in decreased cellular proliferation, and invasion within breast cancer cell lines." (PMID 37705098, 2023). "In a similar fashion, it was demonstrated that DNMT3B bonded to the BECN1 promoter, causing an increase in DNA methylation and a decrease in protein expression in tamoxifen-resistant breast cancer (MCF7/TAMR) cells." (PMID 37571432, 2023). "In breast cancer cells, miR-29c targets and downregulates DNMT3B and reduces the DNA methylation level of TIMP metallopeptidase inhibitor 3 (TIMP3)." (PMID 37298314, 2023). "UXT is highly expressed in breast cancer and combines with DNMT3B to participate in the methylation regulation of MEG3, thus reducing the expression level of MEG3." (PMID 37901333, 2023).